IL6 (interleukin 6)
Diseases named in the same sentence as IL6 in open-access papers (continued):
Sharing a sentence is not in itself a finding about the gene and the disease.
endometriosis (continued). "Moreover, another study found a lack of associations between IL-6 and TNF-α levels and both severity of endometriosis and pain symptoms." (PMID 40507929, 2025). "Together with upregulation of inflammatory mediators such as IL-6, COX-2, and NGF, these findings support a model of widespread immune activation and systemic mast-cell priming, indicating that histamine signaling in endometriosis is both locally active and systemically amplified." (PMID 41516088, 2025). "Additionally, we observed increased levels of IL-6 among the endometriosis cases with severe compared to no/mild dysmenorrhea among those who were taking analgesics." (PMID 40508188, 2025). "Yet another study found that plasma IL-6 levels, but not TNF-α levels, may be useful for differentiating endometriosis from other causes of infertility." (PMID 40507929, 2025). "In addition, TNF-α, endometrial stromal cell-derived IL-6, and monocyte chemoattractant protein (MCP-1) could stimulate peritoneal macrophages toward M2-polarization and modulate endometriosis." (PMID 40507929, 2025). "The study showed that increased serum levels of IL-6 and CA-125 could be used as predictive biomarkers for infertility in women with non-obstructive endometriosis." (PMID 38813329, 2024). "High levels of malondialdehyde (MDA), pro-inflammatory cytokines (IL-6, TNF-α, and IL-1β), angiogenic factors (IL-8 and VEGF), monocyte chemoattractant protein-1 (MCP-1), and oxidized LDL (ox-LDL) were detected in the peritoneal fluid of endometriosis patients." (PMID 36835217, 2023). "Of note, the cytokines inhibited by MiodesinTM, such as IL-8, IL-6, IL-1β, and TNF-α are thought to have a key role in the inflammatory process in endometriosis, becoming an interesting tool as an adjuvant for therapeutic schemes in the treatment of endometriosis." (PMID 35164046, 2022). "There is no doubt that endometriosis patients show elevated levels of expression and release of a range of proinflammatory cytokines and growth factors, including IL-1, IL-6, IL-8, epidermal growth factor and hepatocyte growth factor, in their ectopic and eutopic endometrium and peritoneal fluid." (PMID 36359004, 2022). "In this study, although we could not find any difference in IL-6 and IL-8 levels between endometriosis lesions and eutopic endometrium, we noticed a disruption in IL-1α and IL-1 production, suggestive of endometriosis cells entering the senescence state." (PMID 35269619, 2022). "In addition to these two biomarkers, there are also a number of proteins related to tissue inflammation, including IL-1, IL-6, IL-8, TNF-alpha, ICAM-1, MMPs, TIMPs, or VEGF, that may prove useful for endometriosis detection." (PMID 35453583, 2022). "Our results revealed that HMGB-1 was upregulated in ectopic endometrium, which was also positively correlated with inflammatory cytokines IL-6, TNF-α, and IL-1β, as well as autophagy-related protein beclin-1, suggesting that HMGB-1 might be involved in endometriosis." (PMID 33815277, 2021). "The importance of the let-7 family in the pathophysiology of endometriosis has also been demonstrated in a mouse model, where the introduction of let-7b-5p locally reduced the level of genes known to influence pathogenesis of endometriosis, such as KRAS4A, KRAS4B, ERα, ERβ, Cyp19a, and IL6." (PMID 34449536, 2021). "Tumor necrosis factor-alpha (TNF-α), interleukin one beta (IL-1β), and interleukin six (IL-6) are all elevated as well as the angiogenic factors (VGEF), the growth factors, and adhesion molecules all of which play a positive role in the occurrence, maintenance, and progression of endometriosis." (PMID 33354460, 2020). "Interestingly, consistent with a mild inflammation status, common TH1 cell inflammatory chemokines were more likely to be elevated (IFNγ, IL-12, and IL-6), while other T cell attractants involved in TH2 promotion were decreased in endometriosis patients (TARC and 6Ckine, respectively)." (PMID 31333337, 2019).
endometriosis (continued). "Moreover, transient inhibition or reduction of miR-223 expression exacerbated endometriosis, as indicated by the histological indices, increased NLRP3, IL-1β, IL-6, and TNF-α secretion, as well as the IL-1β-inducible chemokines CXCL1 and CXCL2 mRNA transcripts." (PMID 30186287, 2018). "In addition, we found that the serum levels of COX-2 and IL-6 have no significant fluctuation in the rat model of endometriosis after leuprorelin acetate treatment, which is different from that in human patients." (PMID 27597876, 2016). "Moreover, levels of IL-6 are higher in human endometrial stromal cells derived from the endometrial biopsies of women with endometriosis when compared with women without the disease." (PMID 26198055, 2015). "However, the authors suggest that only IL-6 provides a promising serum marker for nonsurgical diagnosis of endometriosis because IL-6 has higher specificity alone then when adding serum IL-6, MCP-1, and INF-g together." (PMID 24927773, 2014). "In particular, according to these latter authors, increased IL10 production may partially contribute to the disturbed immune regulation in patients with endometriosis, because it attenuates TNF-α-induced IL6 synthesis via NF-kappaB and MAPK pathways in endometriotic cells." (PMID 23843796, 2013). "The recent evidence suggests that ovarian macrophages migration is a result of RANTES secretion into the environment of endometriomas, and their numerous products (IL-1beta, TNF-alfa, Il-6, Il-8, MMP-9, VEGF and others) may be involved in the onset and development of endometriosis." (PMID 16907986, 2006). "Additionally, angiogenesis involving VEGF, inflammatory processes involving substances like IL-1, IL-6, PGE2, COX-2, and SOD, immune responses involving peritoneal macrophages, and hormonal actions involving estrogen and progesterone contribute to the pathogenesis of endometriosis." (PMID 40227209, 2025). "This hypothesis is supported by a study that shows significant production of IL-1beta, IL-6, and TNF-α in endometriotic tissue and another study that found both basal and stimulated synthesis of IL-6 and TNF-α in peritoneal macrophages of women with endometriosis." (PMID 40507929, 2025). "The increased levels of IL-6 in the peripheral blood of patients with endometriosis also suggest that this could be an important cytokine that could be used as a serum marker for non-surgical prediction of endometriosis." (PMID 38892003, 2024). "Therefore, they concluded that the serum IL-6 could be used as an excellent marker to discriminate between the women with and without endometriosis." (PMID 35571503, 2021). "Proportions of Th17 cells also did not correlate with the levels of TGF-β1 and IL-6 which are considered as important factors involved in their development thus further suggesting the limited role of Th17 cells in the pathogenesis of the advanced stages of endometriosis." (PMID 34501240, 2021). "Women affected by endometriosis are more likely than those who were not affected by it to have higher levels of proinflammatory cytokines such as interleukin-1 beta (IL-1), interleukin-6 (IL-6), and tumor necrosis factor-α (TNF-α) occurring locally, in the peritoneal cavity, and systemically." (PMID 33693010, 2020). "These include interleukin (IL)-6, tumor necrosis factor-alpha (TNF-α), and sometimes IL-1β and IL-8, which are significantly increased compared to women without endometriosis." (PMID 41590512, 2026). "Bedaiwy and colleagues demonstrated that measuring serum IL-6 alongside peritoneal TNF-α accurately distinguishes between women with and without endometriosis." (PMID 39767772, 2024). "Up to now, few studies have been interested in comparing IL-6 and AMH levels in women with or without endometriosis." (PMID 36902616, 2023).
endometriosis (continued). "In our study, the analysis of the correlations regarding Ucn1 serum concentrations and cytokines levels including IL-2, IL-4, IL-6, IL-10 and IFN-gamma also brought not so many significant dependencies among women with endometriosis and healthy controls." (PMID 37175494, 2023). "The aim of this study was to compare follicular liquid levels of IL6 and AMH in women with and without endometriosis and to evaluate their potential effect on ICSI outcomes." (PMID 36902616, 2023). "Interleukin (IL)-6 and tumor necrosis factor (TNF)-α are cytokines that are detectable at a higher level in the peritoneal fluid of women with endometriosis than in that without endometriosis." (PMID 36359553, 2022).
ischemic stroke (355 papers, 2007 to 2026). A stroke disorder caused by obstruction of blood flow to the brain, due to thrombotic (local blood clot formation) or embolic (due to a blood clot or other material traveling from another site) event. "Several reviews and metanalyses have demonstrated a strong association between elevated IL-6 levels and increased risk of adverse cardiovascular outcomes, including MI, heart failure, and ischemic stroke." (PMID 41543641, 2026). "Elevated IL‐6 levels have been linearly correlated with an increased long‐term risk of ischemic stroke." (PMID 41367136, 2025). "We decided to use pooled data from the published literature through a systematic review and meta-analysis to investigate the relationship between circulating IL-6 levels and the risk of ischemic stroke in humans." (PMID 40305179, 2025). "Cohort studies have managed to show strong associations between circulating IL-6 levels and the risk of coronary artery disease, but there is limited evidence regarding its associations with ischemic stroke." (PMID 40305179, 2025). "In this study, we aimed to present the functional role of interleukin IL-6 and its association with ischemic stroke." (PMID 40305179, 2025). "The results revealed that HR at T3, MAP at T3, preoperative NLRP3, IL-6, IL-17 levels, and esketamine treatment were all risk factors for cognitive dysfunction in elderly patients undergoing general anesthesia for ischemic stroke." (PMID 40417311, 2025). "Large meta-analyses have demonstrated a dose–response relationship between peripheral IL-6 levels and the risk of ischemic stroke." (PMID 40584526, 2025). "Recent studies have highlighted that inflammatory biomarkers, such as interleukin-6 (IL-6) and (hsCRP), are associated with an increased risk of recurrent cardiovascular events following ischemic stroke or transient ischemic attack." (PMID 40217803, 2025). "Several MR studies provided evidence for a causal effect of interleukin (IL)–6 signaling on ischemic stroke, particularly large artery, and small vessel stroke, supporting the candidacy of IL-6 signaling as a target for prevention." (PMID 38261980, 2024). "IL-6 has been suggested as a potential biomarker for a higher risk of developing HT and brain edema after ischemic stroke." (PMID 38178909, 2023). "Results from Mendelian randomization analyses provided evidence for a causal effect of IL‐6 signaling on ischemic stroke as well." (PMID 37287421, 2023). "Previous studies reported that IL-1, which increased after ischaemic stroke or other risk factors, targeted astrocytes and increased the expression of IL-6, TNF-a, MMP-9, and chemokines." (PMID 36600830, 2023). "It was found that IL-11 (95% CI 0.346~0.799, P = 0.03), NIHSS score, infarct volume, TG, HDLC, and IL-6 were the risk factors for bad prognosis of ischemic stroke patients." (PMID 36875689, 2023). "Other molecular mechanisms that are associated with poorer outcomes in febrile ischemic stroke patients include overexpression of intracellular adhesion molecule 1, interleukin 6, tumour necrosis factor alpha, C-reactive protein, glutamate, and more." (PMID 35366212, 2023). "For each standard deviation increase in log-IL-6 levels, the risk of ischemic stroke increased by 19%." (PMID 37629496, 2023). "It was found that NLRP1, ASITN/SIR grade, infarct volume, NIHSS, IL-6, and IL-1β were the risk factors for bad prognosis of ischemic stroke patients." (PMID 37000063, 2023). "Poor functional outcomes (NIHSS and mRS) after a 3-month follow-up of ischemic stroke patients were associated with high concentrations of IL-6 in serum measured in samples taken within the first 24 h of symptom onset." (PMID 36699006, 2022). "The Framingham study reported that inflammatory markers (such as C-reactive protein, interleukin-6, and fibrinogen) were associated with the risk of ischemic stroke recurrence and transient ischemic attack." (PMID 35756923, 2022).
ischemic stroke (continued). "A linear relationship was found between ischemic stroke risk and circulating IL-6 (potential target for reducing the risk of ischemic stroke) levels." (PMID 36172495, 2022). "Delirium has been associated with increased proinflammatory circulating IL-6 in ischemic stroke patients and in patients after open heart surgery." (PMID 36118695, 2022). "Several neural diseases such as Alzheimer's, Parkinson's and Huntington's diseases, brain cancer and ischemic stroke have all been linked to elevated IL-6 expression and secretion." (PMID 36333451, 2022). "This is the first prospective population-based cohort study exploring the association between the pro-inflammatory IL6 trans-signaling and ischemic stroke in relation to AF." (PMID 34372806, 2021). "Along with TNF-α and IL-1β, IL-6 is also upregulated during the acute inflammatory phase after ischemic stroke and accumulating evidence suggests that elevated IL-6 during acute ischemic stroke is associated with poor functional outcomes." (PMID 34572077, 2021). "IL-6 is also implicated in the development of ischemic stroke, particularly in the occlusion of small brain vessels." (PMID 34683106, 2021). "Several studies have reported that higher levels of inflammatory markers such as CRP and IL‐6 are associated with worse outcome after ischemic stroke." (PMID 33314753, 2021). "The primary aim was to analyze a potential association between IL6 trans-signaling, mirrored by the B/T ratio, and the risk of ischemic stroke in a prospective cohort of middle-aged subjects free of prevalent cardiovascular disease (CVD) with and without AF." (PMID 34372806, 2021). "The aim of the study is however not to find suitable reference values but to analyze associations between IL6 trans-signaling and ischemic stroke." (PMID 34372806, 2021). "Single nucleotide polymorphisms have been found in several genes related to inflammation and ischemic stroke; these polymorphisms include the following: IL-1β, IL-6, IL-10, MMP-2, MMP-9, MMP-12, E-selectin, L-selectin, CD36, PCSK9, and adiponectin." (PMID 33153204, 2020). "Elevated levels of other cytokines, such as monocyte chemoattractant protein 1 (MCP-1), IL-2, IL-6, IL-9, IL-12, IL-18, and chemokine (C-X-C motif) ligand 1, are associated with ischemic stroke." (PMID 33153204, 2020). "For instance, SC downregulated the levels of proinflammatory factors (TNF-α, IL-1β, and IL-6), while upregulated the activities of antioxidant enzymes in cardiomyocyte hypoxia; a complication usually occurs associated with ischemic stroke." (PMID 32240450, 2020). "In the pathology of ischemic stroke, TNFα and IL6 appear to be associated with BBB damage as seen on enhanced magnetic resonance imaging (MRI) scans." (PMID 32432126, 2020). "Classically, three pro-inflammatory cytokines, IL-1β, IL-6, and TNFα are associated with the inflammatory response following ischemic stroke." (PMID 29426336, 2018). "Among microbes for which bacterial counts were significantly associated with ischemic stroke, the L. ruminis subgroup count positively correlated with IL-6 levels." (PMID 28166278, 2017). "Increased numbers of the L. ruminis subgroup were associated with ischemic stroke and were positively correlated with IL-6 levels." (PMID 28166278, 2017). "Prior atorvastatin treatment in patients with ischemic stroke was associated with a lower concentration of IL-6 and TNF-α and improved the outcome of VAP." (PMID 28357403, 2017). "Elevated plasma and CSF levels of IL-6 were associated with increased neurological worsening in patients with ischemic stroke." (PMID 26491692, 2015). "• Blood IL-6 and hFABP levels were independently associated with the functional outcome at three months in patients with ischemic stroke." (PMID 23497639, 2013). "We found that blood IL-6 and hFABP levels are associated with poor clinical outcome in patients with ischemic stroke." (PMID 23497639, 2013).